PRR23C (proline rich 23C)
Synonyms: FLJ46210
Tractability: No criterion of Open Targets' tractability assessment is met for any kind of drug.
Gene: Protein-coding gene on chromosome 3 (139,042,102 to 139,044,892, reverse strand). Ensembl gene ENSG00000233701.
Subcellular location (Human Protein Atlas): Microtubules; Nucleoplasm; Cytokinetic bridge; Cytosol; Mitotic spindle; Nuclear bodies
Genetic constraint (gnomAD): Loss-of-function variants: 3 observed, 1.58 expected, observed/expected ratio (o/e) 1.9, 90% interval 0.64 to 1.95. That is too few expected variants to judge how well the gene tolerates losing a copy. Missense variants: 361 observed, 337.84 expected, observed/expected ratio (o/e) 1.07, 90% interval 0.98 to 1.17. Synonymous variants: 172 observed, 156.16 expected, observed/expected ratio (o/e) 1.1, 90% interval 0.97 to 1.25.
Homologues: Orthologues: chimpanzee PRR23C (99% identical), macaque PRR23C (92% identical), rat Prr23a1 (41% identical), rat Prr23a2 (41% identical), mouse Prr23a1 (41% identical), mouse Prr23a3 (40% identical), rat Prr23a3 (40% identical), mouse Prr23a2 (40% identical), rat Prr23d1 (34% identical), mouse Prr23a4 (23% identical). Paralogues in human: PRR23B (86% identical), PRR23A (86% identical), PRR23D1 (27% identical), PRR23D2 (27% identical), PRR23E (17% identical).